ITGA4 (integrin subunit alpha 4)
Description:
Integrins alpha-4/beta-1 (VLA-4) and alpha-4/beta-7 are receptors for fibronectin. They recognize one or more domains within the alternatively spliced CS-1 and CS-5 regions of fibronectin. They are also receptors for VCAM1. Integrin alpha-4/beta-1 recognizes the sequence Q-I-D-S in VCAM1. Integrin alpha-4/beta-7 is also a receptor for MADCAM1. It recognizes the sequence L-D-T in MADCAM1. On activated endothelial cells integrin VLA-4 triggers homotypic aggregation for most VLA-4-positive leukocyte cell lines. It may also participate in cytolytic T-cell interactions with target cells. ITGA4:ITGB1 binds to fractalkine (CX3CL1) and may act as its coreceptor in CX3CR1-dependent fractalkine signaling. ITGA4:ITGB1 binds to PLA2G2A via a site (site 2) which is distinct from the classical ligand-binding site (site 1) and this induces integrin conformational changes and enhanced ligand binding to site 1. Integrin ITGA4:ITGB1 represses PRKCA-mediated L-type voltage-gated channel Ca(2+) influx and ROCK-mediated calcium sensitivity in vascular smooth muscle cells via its interaction with SVEP1, thereby inhibiting vasocontraction.
Synonyms: CD49d; IA4
Tractability: Small molecule: a drug acting on it is in phase 2 or 3 trials; a structure with a bound ligand is known; a high-quality ligand is known; it belongs to a druggable protein family. Antibody: an approved drug acts on it; its Gene Ontology location is reachable by antibodies, with high confidence; UniProt predicts a signal peptide or a membrane-spanning region; the Human Protein Atlas places it where antibodies can reach. PROTAC: ubiquitination databases record sites on it; its protein half-life has been measured; a small molecule that binds it is known.
Target class: Membrane receptor
Gene: Protein-coding gene on chromosome 2 (181,457,202 to 181,538,940, forward strand). Ensembl gene ENSG00000115232.
Subcellular location: Membrane
Subcellular location (Human Protein Atlas): Plasma membrane
Pathways (Reactome):
Disease: Potential therapeutics for SARS
Extracellular matrix organization: Integrin cell surface interactions
Gene expression (Transcription): RUNX3 Regulates Immune Response and Cell Migration
Hemostasis: Cell surface interactions at the vascular wall
Immune System: Immunoregulatory interactions between a Lymphoid and a non-Lymphoid cell
Gene Ontology:
Molecular function: C-X3-C chemokine binding; cell adhesion molecule binding; protein binding; coreceptor activity; integrin binding; signaling receptor activity; antigen binding; fibronectin binding; protein antigen binding
Biological process: cell-cell adhesion mediated by integrin; cell-matrix adhesion; cell-matrix adhesion involved in ameboidal cell migration; cellular response to amyloid-beta; endodermal cell differentiation; heterotypic cell-cell adhesion; leukocyte cell-cell adhesion; leukocyte tethering or rolling; negative regulation of vasoconstriction; positive regulation of endothelial cell apoptotic process; positive regulation of vascular endothelial cell proliferation; receptor clustering; substrate adhesion-dependent cell spreading; B cell differentiation; cell-cell adhesion; immune response in gut-associated lymphoid tissue; integrin-mediated signaling pathway; axonogenesis involved in innervation; cell adhesion; cellular response to cytokine stimulus; clathrin-dependent extracellular exosome endocytosis; diapedesis; embryonic morphogenesis; import into cell; leukocyte migration; and 6 more
Cellular component: cell surface; extracellular exosome; focal adhesion; integrin alpha4-beta1 complex; integrin alpha4-beta7 complex; membrane; plasma membrane; growth cone; integrin complex; neuronal cell body
Genetic constraint (gnomAD): Loss-of-function variants: 21 observed, 50.18 expected, observed/expected ratio (o/e) 0.42, 90% interval 0.3 to 0.6. The upper end of that interval is the gene's LOEUF score, 0.6, which puts it in group 2 of 6, group 1 being the genes least tolerant of losing a copy. Missense variants: 496 observed, 578.53 expected, observed/expected ratio (o/e) 0.86, 90% interval 0.8 to 0.92. Synonymous variants: 247 observed, 216.61 expected, observed/expected ratio (o/e) 1.14, 90% interval 1.03 to 1.27.
Homologues: Orthologues: chimpanzee ITGA4 (99% identical), macaque ITGA4 (97% identical), pig ITGA4 (90% identical), rabbit ITGA4 (89% identical), dog ITGA4 (88% identical), mouse Itga4 (85% identical), rat Itga4 (85% identical), guinea pig ITGA4 (83% identical), tropical clawed frog itga4 (54% identical), zebrafish itga4 (47% identical), Caenorhabditis elegans pat-2 (22% identical), Drosophila melanogaster if (21% identical), and 3 more. Paralogues in human: ITGA9 (41% identical), ITGA6 (25% identical), ITGAX (25% identical), ITGA8 (24% identical), ITGAD (24% identical), ITGA5 (24% identical), ITGA7 (24% identical), ITGAM (24% identical), ITGA11 (24% identical), ITGAV (24% identical), ITGA1 (23% identical), ITGA2 (23% identical), and 5 more.
Diseases named in the same sentence as ITGA4 in open-access papers:
ITGA4 is named in the same sentence as 156 diseases in open-access papers, as found by Europe PMC text mining. Sharing a sentence is not in itself a finding about the gene and the disease. The quoted sentences say what the papers report.
multiple sclerosis (21 papers, 2006 to 2025). A progressive autoimmune disorder affecting the central nervous system resulting in demyelination. "ITGA4 is associated with multiple sclerosis, autism, and metastasis of cholangiocarcinoma, among others." (PMID 35951140, 2022). "The ITGA4 +3061AG genotype is also associated with the development of multiple sclerosis, which is thought to be mediated by T cells." (PMID 31427644, 2019). "ITGA4 encodes integrin subunit alpha 4, which is overexpressed in nerve injury, promotes immune cell infiltration and inhibited therapeutically in multiple sclerosis." (PMID 35946434, 2022). "Finally, we show that colocalisation of our associations with disease risk signals can suggest aetiological cell-types—variants in IL2RA and ITGA4 respectively mirror the known effects of daclizumab in multiple sclerosis and vedolizumab in inflammatory bowel disease." (PMID 37596262, 2023). "Peptide conjugated phosphorodiamidate morpholino antisense oligomers targeting ITGA4 were also assessed for their effect in delaying disease progression in the experimental autoimmune encephalomyelitis mouse model of multiple sclerosis." (PMID 31506448, 2019). "A humanised monoclonal antibody targeting ITGA4, natalizumab, is an approved drug for treating multiple sclerosis and Crohn’s disease." (PMID 31506448, 2019). "For example, ITGA4, a therapeutic target for multiple sclerosis and Crohn’s disease, was mapped to other autoimmune diseases through our allele-specific analysis." (PMID 28406955, 2017). "Integrin alpha-4 (ITGA4) is a validated therapeutic target for multiple sclerosis (MS) and Natalizumab, an antibody targeting ITGA4 is currently approved for treating MS." (PMID 28487530, 2017). "Indeed, a monoclonal antibody drug targeting ITGA4, natalizumab, is used for treating both multiple sclerosis and Crohn’s disease." (PMID 40702135, 2025). "Up-regulation of ITGA4 has been reported in various malignancies in different studies, such as breast cancer, neuroblastoma and melanoma and immune disorders such as Crohn's disease and multiple sclerosis." (PMID 35075176, 2022). "Similarly, drugs targeting ITGA4 are utilized for the treatment of multiple sclerosis, UC, and CD." (PMID 38707907, 2024). "In this study,ITGA4 expression was significantly increased in CSFCD4+ T-cells when compared with blood CD4+T-cells (log fold change 1.7; FDR = 6.7 × 10−16 and6.5 × 10−16 in NID controls and multiple sclerosis,respectively)." (PMID 34761221, 2021). "For instance, the official gene name ITGA4 is only mentioned twice in context of multiple sclerosis, but searching for all names listed in the ProMiner dictionary retrieves 52 PubMed abstracts containing different synonyms of ITGA4 (integrin alpha 4, CD49d, VLA-4, alpha 4 subunit of VLA-4 receptor)." (PMID 16803617, 2006).
glioma (17 papers, 2015 to 2025). A benign or malignant brain and spinal cord tumor that arises from glial cells (astrocytes, oligodendrocytes, ependymal cells). "TA-MAC, on the other hand, expressed significantly higher levels of Itga4 and Itga1 which have recently been reported to be robust markers for glioma-associated macrophages." (PMID 30602457, 2019). "Several reports suggest elevated levels of ITGA4 denoting macrophage abundance can also predict poor prognosis in gliomas." (PMID 35144680, 2022). "Another useful marker to distinguish MG from infiltrating MΦ is integrin subunit alpha 4 (ITGA4) or CD49D, which was specifically repressed in the MG of different mouse models of glioma." (PMID 33117364, 2020). "The identification of Itga4 (Cd49d) as a monocyte-derived macrophage-specific marker in multiple brain malignancies further confirmed these results in glioma patient samples." (PMID 31611871, 2019). "In addition, microglia-specific inhibition of Itga4 (CD49D) allows it to also serve as a marker for differentiation between microglia and BMDMs in the context of glioma." (PMID 37700840, 2023).
melanoma (17 papers, 2007 to 2025). A malignant, usually aggressive tumor composed of atypical, neoplastic melanocytes. "Analysis based on the cBioPortal database revealed ITGA4 alterations in 22 cancer types, with mutations most common, especially in melanoma." (PMID 40012546, 2025). "As such, Itga4 which was upregulated in WT31_P5IV is associated with melanoma lymph node metastasis." (PMID 37179302, 2023). "ITGA4 is highly expressed in high-risk neuroblastoma, and it can mediate cell invasion and migration in high-risk neuroblastoma and melanoma." (PMID 33335550, 2020). "ITGA4 is closely related to the occurrence and development of melanoma, and ITGA4 can promote the metastasis of melanoma by promoting the aggregation of melanoma cells in the lymphatic system." (PMID 34660316, 2021). "Those that effect a change in cell-cell cohesiveness (e.g. VIM, SPARC, COL4A1, and the integrins, ITGA4 and ITGAV), and have been shown to be over expressed in human or mouse melanoma samples, are each associated with one or more UV-miRNAs." (PMID 27149382, 2016). "Furthermore, the abundant expression of the ITGA4 gene has been found in melanoma cells characterized by its high capabilities to metastasize." (PMID 35742950, 2022). "The immunomodulatory mechanism of ITGA4 in melanoma has also been reported in previous studies." (PMID 34660316, 2021). "ITGA4 achieved an AUC over 0.5 in 13 cohorts, comparable to MSI.Score, and outperformed in predicting NSCLC (Ruppin2021_PD1_NSCLC) and melanoma (Riaz2017_PD1_Melanoma_Ipi.Prog, Gide2019_PD1_Melanoma) immunotherapy outcomes." (PMID 40012546, 2025). "It prompted the genes ITGA4, SPP1, and ITGB3 to promote the interactions between melanoma cells and the ECM and thus facilitated melanoma metastasis." (PMID 35054979, 2022). "ITGA4 is an important molecule involved in homing of HSC and is described to be upregulated in hypoxic environments as ischemic tissues or melanoma cells." (PMID 34876206, 2021). "ITGA4 expression on melanocytes allows adhesion to vascular cell adhesion molecule 1 (VCAM-1) on lymphatic endothelial cells and has been shown to facilitate melanoma lymph node metastases in a mouse model." (PMID 40717170, 2025). "Additionally, ITGA4 expression varied among multiple Immunosuppressive datasets, showing high levels in METABRIC, TCGA Melanoma, ICB_Nathanson2017_CTLA4, and ICB_VanAllen2015_CTLA4 cohorts, but low in GSE12417_GPL570, Patel2017 1, and Shifrut 2018 pilot Average cohorts." (PMID 40012546, 2025). "Finally, CD49d, an α4-integrin (ITGA4) participating in cell-surface mediated signaling and adhesion, was dropped because the antibody failed our validation processes due to generation of multiple bands on western blot using a panel of melanoma cell lines and melanocytes." (PMID 22685558, 2012).
leukemia (13 papers, 2012 to 2024). A malignant (clonal) hematologic disorder, involving hematopoietic stem cells and characterized by the presence of primitive or atypical myeloid or lymphoid cells in the bone marrow and the blood. "To verify whether integrin α4 (ITGA4) is implicated in the adhesion of leukemia cells to MSCs, we knocked down ITGA4 and ITGA5 and examined cell adhesion." (PMID 37453060, 2023). "To further validate the targeting of V9‐HFn‐Se, we detected the expression levels of TfR1 and ITGA4 in different leukemia cells." (PMID 37888866, 2023). "Knocking out ITGA4 restored the sensitivity of BCR-ABL+ murine leukemia toward nilotinib (NTB), and a blockade of integrin alpha 4 with a monoclonal antibody sensitized primary B-ALL engrafted xenograft mice to chemotherapy." (PMID 33425742, 2020). "ITGB1, ITGB3, ITGA4, and ITGA5 were expressed in five of the six leukemia cell lines, and ITGB4 and ITGA6 were specifically expressed in the three EVI1high leukemia cell lines." (PMID 22295105, 2012). "ITGB1 and ITGA4 were expressed as very late antigen-4 (VLA-4) in most of the cell lines, but ITGB4 and ITGA6 were expressed in all three leukemia cell lines and in the two primary EVI1high leukemia cell lines." (PMID 22295105, 2012).
autoimmune disease (10 papers, 2007 to 2025). A disorder resulting from loss of function or tissue destruction of an organ or multiple organs, arising from humoral or cellular immune responses of the individual to their own tissue constituents. "Previously, a variant of ITGA4 was considered a susceptibility locus of autoimmune diseases, especially RA." (PMID 38359008, 2024). "This pattern was consistent for the different disease alleles, indicating that ITGA4 overexpression may be generally associated with an increased risk of autoimmune diseases." (PMID 28406955, 2017). "Although we have not yet identified a similar polymorphism in human α4, we can envisage a scenario in which particular ITGA4 polymorphisms in humans might negatively impact the efficacy of natalizumab for treating neurological disorders as well as other autoimmune diseases." (PMID 21912696, 2011). "Moreover, additional studies are required to fully appreciate the consequences of ITGA4 polymorphisms in the development and treatment of infectious and autoimmune diseases in humans and in their non-human primate models." (PMID 21912696, 2011). "Pro-inflammatory cytokines, such as TNF or IL12A, the T-cell activation molecule CD28, the regulatory molecules IL10, TGFB1 or the adhesion molecules ITGA4 and ITGB1 have all been evaluated previously as therapeutic targets for autoimmune diseases, including MS." (PMID 18030350, 2007).
Sepsis (10 papers, 2016 to 2025). Sepsis is defined as life-threatening organ dysfunction caused by a dysregulated host response to infection. "Upregulated genes identified in sepsis Th17 cell compared to bacteraemia cells were involved in T cell differentiation (ITGA4 and CCR7; 0.80 and 0.41log2FC, respectively), activation, and antigen receptor signalling (CD3G; 0.98log2FC) pathways." (PMID 41208955, 2025). "Interestingly, a previous study revealed VCAM1 overexpressed on endothelial cell-derived extracellular vesicles during sepsis, facilitating the activation of the NF-κB pathway by interacting with integrin subunit alpha 4 (ITGA4) on the monocyte surface thereby regulating monocyte differentiation." (PMID 38956604, 2024). "During sepsis, endothelial cell-derived EVs (EC-EVs) with heightened levels of vascular cell adhesion molecule 1 (VCAM1) stimulate the NF-κB pathway upon binding to integrin subunit alpha 4 (ITGA4) receptors on monocytes." (PMID 39967672, 2025).
chronic lymphocytic leukemia (9 papers, 2015 to 2025). "ITGA4 encodes a member of the integrin α chain family, and its high level is associated with many diseases, such as chronic lymphocytic leukemia, gastrointestinal stromal tumors and colorectal cancer." (PMID 34702302, 2021). "Cut-off values of ITGA4 methylation % of the four CpG sites for chronic lymphocytic leukemia diagnostic and prognostic evaluation." (PMID 32802392, 2020). "ITGA4 is overexpressed in chronic lymphocytic leukemia and associated with migration and retention in lymph node and bone marrow tissues." (PMID 26056562, 2015). "We aimed to investigate ITGA4 gene expression pattern and to explore its methylation heterogeneity in chronic lymphocytic leukemia (CLL)." (PMID 32802392, 2020). "Furthermore, a down-regulation of the ITGA4 gene has also been described in other diseases, such as Crohn ́s disease or the first stages of B-cell chronic lymphocytic leukemia." (PMID 31335901, 2019). "ITGA4 (CD49d) acts as a part of the very late antigen-4 (VLA-4) and has been studied in the context of chronic lymphocytic leukemia (CLL), where it has been found to represent an adverse prognostic marker." (PMID 35681175, 2022).
myeloma (9 papers, 2014 to 2025). "ITGA4 has been demonstrated to be associated with prognosis and immune infiltrates in multiple types of cancer, such as multiple myeloma, breast cancer, and ovarian cancer." (PMID 38270308, 2024). "ITGA4 has previously been implicated in myeloma cell homing, survival, and acquisition of cell-adhesion mediated drug resistance." (PMID 38895237, 2024). "In order to test the association between Itga4 and proliferation in human myeloma, we analyzed publically available datasets from the gene expression omnibus (GEO)." (PMID 34996933, 2022). "The loss of Itga4 produced significant changes in the transcriptome of myeloma cells, affecting functions classically associated with integrins, such as adhesion to the extracellular matrix, cell motility and signaling, but also the structure, metabolism, and homeostatic balance of the cell." (PMID 34996933, 2022). "ITGA4 is an adhesion molecule that is thought to enable multiple myeloma cells to stick to the bone marrow." (PMID 39932005, 2025). "Having found lower myeloma cell prevalence in the BM of mice injected with Itga4 KO 5TGM1 cells, we set out to evaluate homing and osteolysis in 5TGM1 KO MM." (PMID 34996933, 2022). "To assess the intrinsic role of VLA4 to tumor signaling, we deleted the alpha 4 (α4, Itga4) subunit in the WT 5TGM1-GFP murine myeloma cell line using CRISPR/Cas9 technology." (PMID 34996933, 2022). "In all, these results show that ablation of VLA4 through deletion of the ITGA4 (α4) subunit impairs myeloma cell homing and dissemination in the bone, prolonging survival and reducing osteolysis." (PMID 34996933, 2022). "In this study, we generated CRISPR/Cas9-mediated knockout (KO) of the Itga4 (α4) subunit in the VLA4+ 5TGM1-GFP parental murine myeloma cell line (WT 5TGM1) to investigate the biological variation in vitro and in vivo resulting from VLA4 ablation." (PMID 34996933, 2022). "Gene ITGA4 along with ITGB1 codes for integrin VLA4 that mediates homing of myeloma cells into bone marrow and augment IL6 in the microenvironment." (PMID 34040057, 2021). "In myeloid cells, ITGA4 activation leads to tumour inflammation and growth, whereas natalizumab, a recombinant humanized anti‐ITGA4 antibody, decreases myeloma growth by blocking the interaction between myeloma cells and bone marrow stromal cells." (PMID 29377440, 2018).